IQGAP2 (IQ motif containing GTPase activating protein 2)
Diseases named in the same sentence as IQGAP2 in open-access papers (continued):
Sharing a sentence is not in itself a finding about the gene and the disease.
Hepatic steatosis (2 papers, 2013 to 2022). Steatosis is a term used to denote lipid accumulation within hepatocytes. "Apart from the delineated roles of IQGAP1 and IQGAP2, additional research is required to further explore the role of IQGAPs in the pathophysiology of fatty liver disease." (PMID 35785216, 2022). "However, another previous study showed that abrogation of IQGAP2 protects against diet-induced hepatic steatosis due to compromised uptake of fatty acid." (PMID 35785216, 2022).
Hyperglycemia (2 papers, 2014 to 2022). An increased concentration of glucose in the blood. "Iqgap2-deficient mice demonstrated metabolic inflexibility, fasting hyperglycemia, and obesity." (PMID 35328627, 2022).
influenza (2 papers, 2021). An acute viral infection of the respiratory tract, occurring in isolated cases, in epidemics, or in pandemics; it is caused by serologically different strains of viruses (influenzaviruses) designated A, B, and C, has a 3-day incubation period, and usually lasts for 3 to 10 days. "Our study identified two novel candidate missense variants, ZBTB46 rs2281929 and IQGAP2 rs2455230, were associated with the immune response to influenza vaccination among the Chinese population." (PMID 34276655, 2021). "More recently, when genome-wide association studies (GWAS) were employed, two novel candidate missense variants, ZBTB46 rs2281929 and IQGAP2 rs2455230, were found to be associated with the immune response to influenza vaccination among the Chinese population." (PMID 34696202, 2021). "In the combined group, IQGAP2 rs2455230 GC + CC genotype was also correlated with a lower risk of low responsiveness to influenza vaccination compared with the GG genotype (P = 8.90E-04, OR = 0.535, 95%CI = 0.370–0.774), but the difference was not statistically significant in group 2 (P = 0.008)." (PMID 34276655, 2021). "Finally, we observed that ZBTB46 rs2281929 and IQGAP2 rs2455230 are associated with the antibody response to influenza vaccine." (PMID 34276655, 2021). "In the combined group, IQGAP2 rs2455230 GC + CC genotype was correlated with a lower risk of low responsiveness to influenza vaccination compared with the GG genotype (P = 8.90E-04, OR = 0.535, 95%CI = 0.370–0.774), but the difference was not statistically significant in group 2 (P = 0.008)." (PMID 34276655, 2021). "Finally, two SNPs including ZBTB46 rs2281929 and IQGAP2 rs2455230 were found to be significantly correlated with the serological response to influenza vaccine." (PMID 34276655, 2021).
Insulin resistance (2 papers, 2012 to 2021). Increased resistance towards insulin, that is, diminished effectiveness of insulin in reducing blood glucose levels. "T2D genome-wide association analysis meta-analysis revealed two IQ-motif-containing GAPs (IQGAP1 and IQGAP2), involved in cellular signaling, cytoskeletal organization, and GSIS in the top 95th percentile for association with T2D; providing evidence for IQGAP2 contribution to insulin resistance." (PMID 34203728, 2021).
lung carcinoma (2 papers, 2017 to 2021). "Likewise, PPS was also diminished with reduced IQGAP2 expression in lung cancer patients." (PMID 29073199, 2017). "Oncomine analysis of cancer vs. normal tissue in different datasets showed altered expression of IQGAP2 and IQGAP3 in different subtypes of lung cancer." (PMID 29073199, 2017).
melanoma (2 papers, 2017 to 2021). A malignant, usually aggressive tumor composed of atypical, neoplastic melanocytes. "Furthermore, single-cell sequencing showed that IQGAP2 is predominantly expressed on leukocytes but not melanoma cells." (PMID 34034707, 2021).
Obesity (2 papers, 2021 to 2022). Accumulation of substantial excess body fat. "IQGAP2 deficiency influences hepatic free fatty acid uptake, fatty acid synthesis, and lipogenesis, suggesting its importance in obesity." (PMID 34058970, 2021). "Due to high species conservation, the identified genes related to human or mice obesity traits may hold importance for adipose deposition in chickens, such as ELOVL7, IL6ST, IQGAP2, PAX5 and CKMT2." (PMID 34058970, 2021).
primary Sjögren’s syndrome (2 papers, 2021 to 2023). "The up-DPpGCs carry gene fragments and, interestingly, circ-IQGAP2 has been found to be a noninvasive biomarker of primary Sjögren’s syndrome, another rheumatic immune disorder." (PMID 37048133, 2023). "Concerning the possibility that glaucoma is an autoimmune disease, it is worthy to note that in patients with Sjögrens syndrome, a chronic autoimmune disease, an up-regulation of circulating IQGAP2 RNA was identified, while the IQGAP2 protein level was not differentially expressed." (PMID 34943212, 2021).
thyroid cancer (2 papers, 2015 to 2016). "Two of the 18 BRAFV600E-specific genes are believed to be tumor suppressor genes: PDLIM4 and IQGAP2, both previously related to thyroid cancer." (PMID 26625260, 2015). "Other notable genes of unknown function within this list were WSCD2 and IQGAP2, which have previously been reported as downregulated in thyroid cancer." (PMID 27633254, 2016).
anaplastic oligoastrocytoma (1 paper, 2017). An oligoastrocytoma characterized by the presence of increased cellularity, nuclear atypia, pleomorphism, and high mitotic activity. "Similarly, the mRNA expression of IQGAP2 was high in diffuse astrocytoma (fold change = 3.78), oligodendroglioma (fold change = 2.05), anaplastic oligoastrocytoma (fold change = 4.83) and anaplastic oligodendroglioma (fold change = 2.77)." (PMID 29073199, 2017).
brain cancer (1 paper, 2017). A primary or metastatic malignant neoplasm affecting the brain. "In brain cancer, a significant over expression of IQGAP2 was observed in different independent datasets of Oncomine." (PMID 29073199, 2017). "Interestingly, in contrast to the expression pattern in other cancers, IQGAP2 mRNA levels were upregulated in all major subtypes of primary brain cancers." (PMID 29073199, 2017). "As far as prognosis is concerned, increase in both IQGAP2 and IQGAP3 mRNA levels correlated with poor overall survival of brain cancer patients." (PMID 29073199, 2017).
brain tumor (1 paper, 2017). "Likewise, in brain tumor 12.25%, 26.5% and, 61.2% samples showed strong, moderate, and weak staining for IQGAP2, respectively." (PMID 29073199, 2017).
breast tumors (1 paper, 2017). "Our finding suggests that IQGAP2 also merits future investigation with regards to its role in progression of breast tumors of ductal origin." (PMID 29073199, 2017).
carotid atherosclerosis (1 paper, 2021). A thickening and loss of elasticity of the walls of carotid arteries that occur with formation of atherosclerotic plaques. "NCF2, IQGAP2, and CD86 might play crucial roles in the process of carotid atherosclerosis." (PMID 33613306, 2021).
Cirrhosis (1 paper, 2010). A chronic disorder of the liver in which liver tissue becomes scarred and is partially replaced by regenerative nodules and fibrotic tissue resulting in loss of liver function. "The expression of IQGAP2 was diffusely positive in the hepatocytes of 22/28 (78.6%) normal livers, 4/4 (100.0%) hepatic adenomas and 23/23 (100.0%) cirrhosis cases." (PMID 20977743, 2010). "No IQGAP1 staining was detected in 23/28 (82.1%) normal livers, 4/4 (100.0%) hepatic adenomas and 23/23 (100.0%) cirrhosis cases, while IQGAP2 was increased in 22/28 (78.6%), 4/4 (100.0%) and 23/23 (100.0%), respectively." (PMID 20977743, 2010). "The hepatic adenomas and cirrhosis cases had Iqgap2 methylation levels comparable to that of normal livers (2.3% and 3.3%, respectively)." (PMID 20977743, 2010). "Similarly, IQGAP2 was negative in 78.0% of HCCs, but was positive in 100%, 100% and 78.6% of hepatic adenomas, cirrhosis cases and normal livers, respectively." (PMID 20977743, 2010).
colon adenocarcinoma (1 paper, 2017). "TCGA-COADREAD analysis showed low IQGAP2 mRNA expression in colon adenocarcinoma (fold change = -2.04), colon mucinous adenocarcinoma (fold change = -1.18) and rectal adenocarcinoma (fold change = -1.90) but no change in rectal mucinous adenocarcinoma." (PMID 29073199, 2017).
Crohn disease (1 paper, 2018). A gastrointestinal disorder characterized by chronic inflammation involving all layers of the intestinal wall, noncaseating granulomas affecting the intestinal wall and regional lymph nodes, and transmural fibrosis. "As IQGAP2 has been implicated in colonic inflammation in mice, we explored whether its expression was different in patients with Crohn’s Disease compared to controls, using RNA-seq data derived from the colon in 76 cases and 28 controls." (PMID 29715290, 2018).
diabetic nephropathy (1 paper, 2024). "Looking at the expression levels of these proteins in patients suffering from diabetic nephropathy (DN), we found a down-regulation of the expression (log2 fold change: SIRPA: -0.902; IQGAP2: -0.578)." (PMID 38605154, 2024).
diffuse large B-cell lymphoma (1 paper, 2023). "However, IQGAP2 is a negative prognostic factor and is associated with immunosuppression in diffuse large B-cell lymphoma." (PMID 37543576, 2023).
ductal breast carcinoma (1 paper, 2017). "Based on these observations, we speculated that IQGAP2 might play a crucial role in ER positive ductal breast carcinoma." (PMID 29073199, 2017).
ductal breast carcinoma in situ (1 paper, 2017). A carcinoma entirely confined to the mammary ducts. "In Ma Breast dataset, reduced IQGAP2 expression was observed in ductal breast carcinoma in situ (fold change = -2.65) and in invasive ductal breast carcinoma (fold change = -2.86)." (PMID 29073199, 2017).
endothelial dysfunction (1 paper, 2023). In vascular diseases, endothelial dysfunction is a systemic pathological state of the endothelium (the inner lining of blood vessels) and can be broadly defined as an imbalance between vasodilating and vasoconstricting substances produced by (or acting on) the endothelium. "Moreover, it has been demonstrated that ATP2B1-AS1 acts as a miR-4729 sponge to regulate the expression of IQGAP2, reducing high-glucose-induced endothelial dysfunction in DR." (PMID 36998473, 2023).
glioblastoma (1 paper, 2017). The most malignant astrocytic tumor (WHO grade IV). "The expression levels of IQGAP2 were elevated in glioblastoma (GMB), in Sun brain, Murat brain and, in TCGA brain dataset." (PMID 29073199, 2017).
hepatitis B virus (1 paper, 2019). "Six IA genes, APOB, IMPDH1, SEC61G, IQGAP2, TAGAP, and IGKV4-1, were dysregulated (differential expression, p < 0.05) in only tumor samples of drinkers without hepatitis B virus (HBV) infection as compared to pure normal samples (from nondrinkers)." (PMID 31480259, 2019).
Hypertension (1 paper, 2016). The presence of chronic increased pressure in the systemic arterial system. "Notably, SUMF1, F2R and IQGAP2 (found in the case group) and ACSF3 (found in the control group) identified in the initial study were replicated in the replication cohort, suggesting potential role of these genes in pathophysiology of hypertension related LVH." (PMID 26930585, 2016).
inflammatory bowel disease (1 paper, 2015). A spectrum of small and large bowel inflammatory diseases of unknown etiology. "The goal of this study was to determine the contribution of IQ motif-containing GTPase-activating protein 2 (IQGAP2) to inflammation of the gastrointestinal tract, the central disease-causing feature of inflammatory bowel disease (IBD)." (PMID 26047140, 2015). "Finally, alterations in IQGAP2 expression were found in colons of patients with inflammatory bowel disease (IBD)." (PMID 26047140, 2015).
kidney chromophobe (1 paper, 2022). "IQGAP2 was downregulated in tumor tissues of kidney renal clear cell carcinoma (KIRC) and kidney renal papillary cell carcinoma (KIRP), and upregulated in tumor tissues of kidney chromophobe (KICH) (data were not shown)." (PMID 36275458, 2022).
lung adenocarcinoma (1 paper, 2017). A carcinoma that arises from the lung and is characterized by the presence of malignant glandular epithelial cells. "TCGA-LUNG, showed reduced expression of IQGAP2 in lung adenocarcinoma mixed type (fold change = -1.0) and in lung squamous cell carcinoma (fold change = -2.06), but not in lung papillary adenocarcinoma and mucinous cell lung carcinoma." (PMID 29073199, 2017). "In Bhattacharjee lung dataset, the mRNA level of IQGAP2 was significantly decreased in lung carcinoid tumor (fold change = -4.95) and lung adenocarcinoma (fold change = -2.60)." (PMID 29073199, 2017).
psoriasis (1 paper, 2022). An autoimmune condition characterized by red, well-delineated plaques with silvery scales that are usually on the extensor surfaces and scalp. "Further studies confirming the functional implication of IQGAP2/F2RL2 in psoriasis and the response to anti-TNF agents are warranted." (PMID 36059983, 2022).
pterygium (1 paper, 2020). A wedge-shaped fibrovascular lesion arising from the bulbar conjunctiva and extending to the cornea. "Our study may provide new insights into the role of IQGAP2 in the mechanisms of pterygium pathogenesis." (PMID 32411530, 2020). "The expression of the five hub genes (ECM1, IQGAP2, FN1, GADD34, CXCL12) was determined by real-time PCR in comparisons between 10 normal conjunctival tissues and 10 pterygium tissues." (PMID 32411530, 2020). "However, the functions of IQGAP2 in pterygium have not been addressed." (PMID 32411530, 2020).
Salmonella Infections (1 paper, 2019). Infections with bacteria of the genus SALMONELLA. "The observed upregulation of miR-124 expression and downregulation of IQGAP2 expression indicated that the CDC42-MAPK pathway is highly possibly inhibited after Salmonella infection." (PMID 31186019, 2019).
triple-negative breast carcinoma (1 paper, 2021). An invasive breast carcinoma which is negative for expression of estrogen receptor (ER), progesterone receptor (PR), and human epidermal growth factor receptor 2 (HER2). "Via sponging miR-10b-5p to upregulate IQGAP2, lncRNA PDCD4-AS1, a downregulated in both triple-negative breast cancer tissues and cell lines and can suppress tumor progression." (PMID 34631703, 2021).
viral infections (1 paper, 2019). "It is also possible that SENP3 may be a central viral stress sensor and protector of host translation—it responds to different viral infections by degrading IQGAP2 to boost Akt phosphorylation." (PMID 30640896, 2019).
tumor (45 papers, 2010 to 2025). "Live small animal fluorescent imaging assays showed that the knockdown of IQGAP2 abrogated suppressive impact on tumor metastasis caused by ALDH9A1 overexpression." (PMID 39039052, 2024). "It has been reported that IQGAP2 is essential for cell-cell adhesion, therefore, decreased IQGAP2 in tumor tissues also causes decreased cell-cell adhesion and promotes tumor cell metastasis and implantation to other normal liver tissues or organs." (PMID 36320006, 2022). "Other clinical studies also showed that low expression of IQGAP2 was strongly associated with larger tumor size, multiple tumor lesions, poorer tumor differentiation, and shorter postoperative RFS and OS." (PMID 36320006, 2022). "Our patient data showed an association of reduced IQGAP2 expression with higher lymph node metastasis and lymphovascular invasion, which is a testimony to the crucial tumor-suppressing ability of this protein." (PMID 33846302, 2021). "Though IQGAP2 methylation was reported to correlate with tumor invasion and poor prognosis of GCs, the role and underlying mechanism of IQGAP2 in GC cells migration and invasion remain to be elucidated." (PMID 32183047, 2020). "Breeding of Iqgap2-null mice with Iqgap1-null mice resulted in reduced HCC phenotype suggesting that Iqgap2 acts as a tumor suppressor and its loss can lead to β-catenin activation and HCC development." (PMID 32093152, 2020). "To more comprehensively examine molecular changes responsible for the Iqgap2−/− tumorigenic phenotype and to gain an insight into mechanisms underlying the tumor suppressive function of IQGAP2, we next compared age-dependent changes in transcript expression between WT and KO livers." (PMID 23951254, 2013). "Interestingly, Schmidt and coworkers suggested that Iqgap2 acts as a tumor suppressor, and its loss can lead to β-catenin activation and the development of HCC, and this finding further implicates β-catenin as a key driver of HCC." (PMID 21545718, 2011). "In the IQGAP family, the expression of IQGAP2 is reduced and acts as a tumor suppressor in most solid cancer types, while IQGAP3 is overexpressed and functions as an oncogene." (PMID 40361412, 2025). "Taken together, these results validated that ALDH9A1 exerted tumor suppressor role and metabolic reprogramming role by repressing the expression of IQGAP2 and activating the AKT-mTOR-SREBP1 pathway in ccRCC." (PMID 39039052, 2024). "The tumor weight and tumor volume in the ALDH9A1-overexpressing group were significantly decreased, while the additional knockdown of IQGAP2 reversed this inhibition caused by ALDH9A1 overexpression." (PMID 39039052, 2024). "Decreased IQGAP2 expression is related with increased tumor size, advanced tumor stage, worse tumor differentiation, as well as shorter postoperative tumor-free survival and overall survival after hepatectomy." (PMID 36831467, 2023). "In contrast, IQGAP2 expression is decreased in several malignancies, suggesting that it is a tumor suppressor." (PMID 37071417, 2023). "IQGAP2 expression is reduced and plays a tumor suppressor role in most solid cancer types, while IQGAP3 is overexpressed and acts as an oncogene." (PMID 36831467, 2023). "Despite its 62% sequence homology with other IQGAPs, the majority of evidence demonstrated that IQGAP2 acted as a tumor suppressor in malignancies." (PMID 36831467, 2023). "IQGAP2 expression is reduced and plays a tumor suppressor role in most solid cancer types, while IQGAP3 is overexpressed and acts as an oncogene in the same cancer types." (PMID 36831467, 2023). "Conversely, positive IQGAP2 expression predicted less tumor numbers and microvascular invasion, as well as higher RFS and OS in these patients." (PMID 36320006, 2022). "IQGAP2 is predominantly expressed in the liver, and multiple studies have shown that IQGAP2 exerts tumor-suppressive effects in a variety of cancers." (PMID 36320006, 2022).